PDE1B (phosphodiesterase 1B)
Description:
Cyclic nucleotide phosphodiesterase with a dual specificity for the second messengers cAMP and cGMP, which are key regulators of many important physiological processes. Has a preference for cGMP as a substrate.
Synonyms: PDES1B; HEL-S-79p; PDE1B1
Tractability: Small molecule: an approved drug acts on it; a structure with a bound ligand is known; a high-quality ligand is known; it belongs to a druggable protein family. PROTAC: its protein half-life has been measured; a small molecule that binds it is known.
Target class: Enzyme; Phosphodiesterase 1; Phosphodiesterase; Phosphodiesterase 1B
Chemical probes: ITI-214 (high quality)
Gene: Protein-coding gene on chromosome 12 (54,549,601 to 54,579,241, forward strand). Ensembl gene ENSG00000123360.
Subcellular location: Cytoplasm, cytosol
Pathways (Reactome):
Signal Transduction: Cam-PDE 1 activation; G alpha (s) signalling events
Hemostasis: cGMP effects
Gene Ontology:
Molecular function: 3',5'-cyclic-AMP phosphodiesterase activity; 3',5'-cyclic-GMP phosphodiesterase activity; 3',5'-cyclic-nucleotide phosphodiesterase activity; calmodulin-activated dual specificity 3',5'-cyclic-GMP, 3',5'-cyclic-AMP phosphodiesterase activity; protein binding; cyclic-nucleotide phosphodiesterase activity; phosphoric diester hydrolase activity
Biological process: cellular response to granulocyte macrophage colony-stimulating factor stimulus; cellular response to macrophage colony-stimulating factor stimulus; monocyte differentiation; negative regulation of cAMP/PKA signal transduction; signal transduction
Cellular component: cytosol; neuronal cell body
Genetic constraint (gnomAD): Loss-of-function variants: 13 observed, 54.85 expected, observed/expected ratio (o/e) 0.24, 90% interval 0.15 to 0.38. The upper end of that interval is the gene's LOEUF score, 0.38, which puts it in group 1 of 6, group 1 being the genes least tolerant of losing a copy. Missense variants: 400 observed, 597.24 expected, observed/expected ratio (o/e) 0.67, 90% interval 0.62 to 0.73. Synonymous variants: 198 observed, 227.03 expected, observed/expected ratio (o/e) 0.87, 90% interval 0.78 to 0.98.
Homologues: Orthologues: chimpanzee PDE1B (99% identical), pig PDE1B (97% identical), guinea pig PDE1B (96% identical), rabbit PDE1B (96% identical), mouse Pde1b (96% identical), rat Pde1b (96% identical), macaque PDE1B (94% identical), dog PDE1B (89% identical), tropical clawed frog pde1b (81% identical), Caenorhabditis elegans pde-3 (23% identical), Drosophila melanogaster Pde11 (23% identical), Caenorhabditis elegans pde-6 (21% identical), and 1 more. Paralogues in human: PDE1C (60% identical), PDE1A (56% identical), PDE3B (29% identical), PDE4D (29% identical), PDE4B (28% identical), PDE3A (28% identical), PDE4A (27% identical), PDE4C (27% identical), PDE6C (25% identical), PDE8A (25% identical), PDE11A (25% identical), PDE8B (25% identical), and 8 more.
Diseases named in the same sentence as PDE1B in open-access papers:
PDE1B is named in the same sentence as 28 diseases in open-access papers, as found by Europe PMC text mining. Sharing a sentence is not in itself a finding about the gene and the disease. The quoted sentences say what the papers report.
osteosarcoma (4 papers, 2023 to 2025). A usually aggressive malignant bone-forming mesenchymal neoplasm, predominantly affecting adolescents and young adults. "The PDE1B gene was discovered to be lowly expressed in osteosarcoma, and its low expression was associated with poor OS (all P < 0.05)." (PMID 38877061, 2024). "All of these five signaling pathways were significantly linked with osteosarcoma, and the PDE1B gene was predicted to play vital roles via these pathways in osteosarcoma." (PMID 38877061, 2024). "GSEA was applied by us to reveal PDE1B related pathways in osteosarcoma, and our outcomes showed that PDE1B was markedly linked to calcium, cell cycle, chemokine, JAK STAT, and VEGF pathways." (PMID 38877061, 2024). "In our article, the PDE1B gene was discovered to be lowly expressed in osteosarcoma, and its low expression was significantly associated with poor OS." (PMID 38877061, 2024). "All of these indicated the vital associations between PDE1B gene expression and immunity in osteosarcoma." (PMID 38877061, 2024). "Moreover, PDE1B was significantly associated with OS in the TARGET osteosarcoma dataset, with a cut-off value of P value below 0.05." (PMID 38877061, 2024). "investigates the role of PDE1B in osteosarcoma, suggesting that PDE1B is a tumor suppressor gene that prevents osteosarcoma from escaping the immune system." (PMID 41179677, 2025). "We also established a nomogram based on several clinical factors (gender, race, first event, disease at diagnosis, and PDE1B gene expression) to further forecast the 1-, 3-, 5-year OS probabilities of osteosarcoma patients intuitively with good performance." (PMID 38877061, 2024). "C-index and 1-, 3-, 5-year AUCs of the PDE1B-based nomogram were 0.867, 0.892, 0.899, and 0.873 in the Target osteosarcoma dataset, respectively." (PMID 38877061, 2024). "Univariate and multivariate Cox regression analyses indicated that the PDE1B gene had independent abilities in predicting OS for osteosarcoma." (PMID 38877061, 2024). "Phosphodiesterase 1B (PDE1B) has also been considered a potential biomarker associated with TME and clinical significance in osteosarcoma." (PMID 39154307, 2024). "The PDE1B gene was found to be a tumor suppressor gene in osteosarcoma, and its high expression was related to a better OS prognosis, suppressing immune escape from osteosarcoma." (PMID 38877061, 2024). "Univariate and multivariate Cox regression analyses indicated that the PDE1B gene had independent abilities in predicting OS in the TARGET osteosarcoma dataset." (PMID 38877061, 2024). "Further TIDE algorithms shed light on that patients with high-PDE1B expression would have a better immune response to immunotherapies than those with low-PDE1B expression in osteosarcoma." (PMID 38877061, 2024). "PDE1B high expression was related to a better tumor prognosis, suppressing immune escape from osteosarcoma." (PMID 39154307, 2024). "The PDE1B gene was found to be a tumor suppressor gene in osteosarcoma, related to OS prognosis and immunity." (PMID 38877061, 2024). "Univariate and multivariate Cox regression analyses indicated that the PDE1B gene had independent abilities in predicting OS in the TARGET osteosarcoma dataset (both P < 0.05)." (PMID 38877061, 2024). "In this article, we firstly mined three osteosarcoma related datasets (GSE28424, GSE33382 and TARGET osteosarcoma datasets) and identified a total of 10 intersected genes by Venn diagram, including the PDE1B gene." (PMID 38877061, 2024). "Experimental verification of the PDE1B gene in osteosarcoma was conducted by qRT-PCR and western blot, based on the manufacturer's instructions." (PMID 38877061, 2024). "GSEA was applied by us to reveal PDE1B related pathways in osteosarcoma, and the outcomes of us showed that PDE1B was markedly linked to the calcium, cell cycle, chemokine, JAK STAT, and VEGF pathways." (PMID 38877061, 2024).
osteosarcoma (continued). "The major limitation was that the current paper was only a preliminary exploration of the role of PDE1B in osteosarcoma, which was more based on theoretical analysis." (PMID 38877061, 2024). "Experimental verifications by qRT-PCR and western blot results indicated that both PDE1B gene mRNA and protein expression levels were lowly expressed in osteosarcoma cell lines (all P < 0.05)." (PMID 38877061, 2024). "As for immune checkpoints genes, our results reported that the PDE1B gene was significantly involved with immune checkpoints genes in osteosarcoma." (PMID 38877061, 2024). "In this article, we firstly mined the prognostic values and immunological roles of the PDE1B gene in osteosarcoma with the assistance of experimental verifications, making our results much more reliable." (PMID 38877061, 2024). "This article provided some references for future PDE1B related research in osteosarcoma and was anticipated to provide operational targets for future clinically personalized treatment targets for osteosarcoma." (PMID 38877061, 2024). "Currently, little was known about the definite role of PDE1B in osteosarcoma." (PMID 38877061, 2024). "All of these suggested that elevated PDE1B gene expression could prevent immune escape from osteosarcoma." (PMID 38877061, 2024). "Evaluating osteosarcoma patients’ PDE1B gene expression for immunotherapies by TIDE dataset." (PMID 38877061, 2024). "Therefore, we mined public data on osteosarcoma to reveal the prognostic values and immunological roles of the PDE1B gene, providing operational targets for further clinically personalized treatment targets in osteosarcoma." (PMID 38877061, 2024). "Therefore, the present article was aimed at mining public data on osteosarcoma to reveal the prognostic values and immunological roles of the PDE1B gene in osteosarcoma, with the assistance of experimental verifications." (PMID 38877061, 2024). "Therefore, we mined public data on osteosarcoma to reveal the prognostic values and immunological roles of the PDE1B gene." (PMID 38877061, 2024). "PDE1B was identified as potential prognostic biomarkers in osteosarcoma." (PMID 36807122, 2023). "Further TIDE algorithms shed light on that patients with high-PDE1B expression would have a better immune response to immunotherapies than those with low-PDE1B expression, suggesting that elevated PDE1B gene expression could prevent immune escape from osteosarcoma." (PMID 38877061, 2024). "However, little was known about the definite role of PDE1B in osteosarcoma." (PMID 38877061, 2024). "The Venn diagram showed that a total of 10 intersected genes were obtained from three osteosarcoma-related datasets (GSE28424, GSE33382, and TARGET osteosarcoma datasets), including the PDE1B gene." (PMID 38877061, 2024).
schizophrenia (3 papers, 2019 to 2026). A major psychotic disorder characterized by abnormalities in the perception or expression of reality. "Inhibitors of PDE1B may be particularly suited for the treatment of cognitive impairment associated with schizophrenia (CIAS)." (PMID 30792627, 2019). "Several reports have suggested that PDE10A inhibitors may present a promising approach for the treatment of positive symptoms of schizophrenia, whereas PDE1B inhibitors may present a novel mechanism to modulate cognitive deficits." (PMID 36454774, 2022). "Herein, we have shown that a dual inhibitor of PDE1B and PDE10A, compound 2, prevented and reversed schizophrenia-like behavioural alterations induced by ketamine, suggesting the potential of compound 2 as a promising therapy for schizophrenia." (PMID 36454774, 2022). "By addressing the limitations of current candidates and emphasizing the need for dual inhibitors, this review aims to guide future research efforts toward the discovery of more selective, potent, and clinically viable PDE1B and PDE10A inhibitors for schizophrenia." (PMID 41835457, 2026). "Together, these mechanisms suggest that targeting PDE1B and PDE10A could offer an innovative avenue for the comprehensive management of schizophrenia." (PMID 41835457, 2026).
cognitive deficits (2 papers, 2022 to 2026). "PDE1B inhibition enhances D1-receptor signaling, ameliorating negative symptoms and cognitive deficits, while PDE10A inhibition modulates D2-receptor activity, potentially alleviating positive symptoms." (PMID 41835457, 2026). "The inhibition of PDE1B activity in the prefrontal cortex potentiates the D1-receptor signalling and mitigates the negative symptoms and cognitive impairments." (PMID 36454774, 2022).
allergic disease (1 paper, 2023). An immune response that occurs following re-exposure to an innocuous antigen, and that requires the presence of existing antibodies against that antigen. "Some calcium signaling pathway-related genes, such as ERBB2, PDE1B, PDGFA, TPCN1, and MCU, have been reported to participate in the development of allergic diseases." (PMID 37328853, 2023).
clear cell renal cell carcinoma (1 paper, 2024). "PDE1B can be targeted by miR-5701 to inhibit proliferation and promote apoptosis of clear cell renal cell carcinoma cells." (PMID 38396187, 2024).
diabetes (1 paper, 2023). "We discovered by data analysis and review of the literature that Dgkh, Clasp1, and Pde1b are linked to central nervous system disease; however, only Dgkh showed reduced levels in the case of diabetes and HG-treated HN-h cells." (PMID 37385994, 2023).
Huntington disease (1 paper, 2022). Huntington disease (HD) is a rare neurodegenerative disorder of the central nervous system characterized by unwanted choreatic movements, behavioral and psychiatric disturbances and dementia. "As Huntington’s disease is associated with a reduced transcription of cyclic AMP early in the disease, we observed a downregulation in the expression of PDE10A and PDE1B, two cAMP/cGMP phosphodiesterases highly expressed in MSNs." (PMID 36523271, 2022).
ischemic stroke (1 paper, 2020). A stroke disorder caused by obstruction of blood flow to the brain, due to thrombotic (local blood clot formation) or embolic (due to a blood clot or other material traveling from another site) event. "By inhibiting PDE1-B in microglial cells, vinpocetine does not only inhibit the M1 microglial phenotype but also enhance autophagic flux which is associated with the alteration of exosomal contents and properties for protecting the survival and neurite structure of neurons against ischemic stroke." (PMID 33614626, 2020). "To explore the role of PDE1-B in microglia after ischemic stroke, we firstly used the intraluminal suture-mediated transient and permanent MCAO models in mice." (PMID 33614626, 2020). "To investigate the potential role of PDE1-B and the effect of its inhibitor vinpocetine on microglial function, we used BV2 cells and the OGD model to examine the microglial response under ischemic stroke condition in vitro." (PMID 33614626, 2020).
liver cirrhosis (1 paper, 2014). "Two of these CNVs, located at 13q12.11 and 12q13.2 respectively, harbour the exportin 4 (XPO4) and phosphodiesterase 1B (PDE1B) genes which are already known to be involved in the etiology of liver cirrhosis and HCC." (PMID 24743702, 2014).
liver disease (1 paper, 2014). "However, there are a limited number of published reports on XPO4 and PDE1B and their putative role in liver disease." (PMID 24743702, 2014).
memory impairment (1 paper, 2019). "Inhibition of PDE1B is a promising therapeutic mechanism for treating memory impairment." (PMID 30792627, 2019).
renal cell carcinoma (1 paper, 2021). "In renal cell carcinoma miR-5701 promoted apoptosis by targeting phosphodiesterase-1B." (PMID 34827683, 2021).
Stroke (1 paper, 2020). Sudden impairment of blood flow to a part of the brain due to occlusion or rupture of an artery to the brain. "Nevertheless, whether and how PDE1B mediates neuroprotective mechanism in stroke remains incompletely understood." (PMID 33614626, 2020).
tumor (5 papers, 2009 to 2025). "In terms of tumor microenvironment, our results presented that PDE1B gene expression was significantly associated with immune, ESTIMATE, and stromal scores by the ESTIMATE algorithm." (PMID 38877061, 2024). "In the case of tumor immune cells infiltration levels, PDE1B was found to be markedly associated with T cells gamma delta and Macrophages M0 cells infiltration levels." (PMID 38877061, 2024). "Moreover, PDE1B was found to be markedly associated with immunity, including the T cells gamma delta, Macrophages M0 cell infiltration levels, and the tumor microenvironment." (PMID 38877061, 2024). "In clear cell renal cell carcinoma, PDE1B was found to be the target of miR-5701 in promoting the tumor cells’ apoptosis." (PMID 38877061, 2024). "Tumor immune cells infiltration levels were calculated by the CIBERSORT algorithm to assess the infiltration levels of 22 kinds of immune cells in high-PDE1B and low-PDE1B subgroups." (PMID 38877061, 2024). "Several genes were classified with function involved in DNA repair, apoptosis and tumor formation such as BOK which encodes a Bcl-2 related protein and PDE1B which may play a role in apoptosis." (PMID 19193219, 2009). "The tumor microenvironment was calculated by the ESTIMATE algorithm to assess immune, ESTIMATE, and stromal scores in high-PDE1B and low-PDE1B subgroups." (PMID 38877061, 2024). "Compared with metastatic tumor tissues, the expression of ABCG8 and LOXL4 was higher, whereas that of PDE1B was lower, which was concordant to our findings using the TCGA database." (PMID 33564309, 2021).
cancer (2 papers, 2020 to 2024). A tumor composed of atypical neoplastic, often pleomorphic cells that invade other tissues. "Phosphodiesterase 1 (PDE1s: PDE1A; PDE1B; PDE1C) targets second messengers (cAMP and cGMP) to regulate diverse physiological processes, with limited exploration in cancer." (PMID 38962317, 2024). "Yet, data on the role of GSTM5, PDE6B, SGPP2, PDE1B, DGKB, and PLCG2 in cancer are still lacking." (PMID 33282950, 2020).
central nervous system disease (1 paper, 2023). "By analyzing our data and reviewing the literature, we found that Dgkh, Clasp1 (cytoplasmic linker-associated protein 1), and Pde1b (phosphodiesterase 1b) are closely related to central nervous system disease." (PMID 37385994, 2023).
movement disorder (1 paper, 2025). Neurological conditions resulting in abnormal voluntary or involuntary movement, which may impact the speed, fluency, quality and ease of movement. "We here present a novel syndrome of axial hypotonia in infancy with progressive movement disorder throughout childhood that is caused by biallelic variants in PDE1B." (PMID 40492975, 2025). "Biallelic loss‐of‐function variants in PDE1B underlie a novel early‐onset movement disorder resembling the phenotype associated with PDE10A deficiency." (PMID 40492975, 2025). "Altogether, we have identified and characterized a novel monogenic movement disorder caused by biallelic PDE1B variants." (PMID 40492975, 2025). "Thus, advances in developing treatment modalities for common hyperkinetic and hypokinetic movement disorders, such as HD and PD,1, 5 might be conducive to achieving effective treatment of the rare PDE1B disease, and vice versa." (PMID 40492975, 2025).
nervous system diseases (1 paper, 2021). "The mRNAs of Rgs9, Gpr88, Drd2, Sh3rf2, Tac1, Serpina 9, Rxrg, Drd1, Rasgrp2, Six3, Gpr6, Pdyn, Gng7, and Pde1b were all upregulated (p < 0.05); all of these have been reported to be more or less related to nervous system diseases." (PMID 33819195, 2021).
PDE1B also shares sentences with these, for which no sentence is quoted: asthma (1 paper); breast carcinoma (1); colon cancer (1); COVID-19 (1); Dyskinesia (1); endotoxemia (1); infection (1); Parkinson disease (1); R6 (1); triple-negative breast carcinoma (1).